CA9 (carbonic anhydrase 9)
Diseases named in the same sentence as CA9 in open-access papers (continued):
Sharing a sentence is not in itself a finding about the gene and the disease.
tumor (continued). "In HCC, CA9 upregulation promotes tumor progression by modulating cell proliferation, apoptosis, and epithelial-mesenchymal transition (EMT)." (PMID 41357200, 2025). "These histocultures were all shown to be highly positive for CA9 by immunostaining at baseline, a surrogate for tumour hypoxia and acidity." (PMID 41375084, 2025). "Another upregulated gene is CA9, a hypoxia-responsive gene that is upregulated in the hypoxic tumour microenvironment." (PMID 40871563, 2025). "In this study, we first reveal the unique mechanism by which HBO inhibits CA9 and acidifies the pHi of both tumor cells and CSCs." (PMID 40873634, 2025). "Clinically, high expression of HIF-1α and CA9 correlates with advanced tumor grade and poorer survival in sarcoma patients." (PMID 41174561, 2025). "There were extensive microvascular structures within the VTT, with CD31+ vessels surrounded by alpha smooth muscle actin (SMA) positive pericytes, between the CA9+ tumour cells." (PMID 40295487, 2025). "In keeping with previous studies, VTT consisted mainly of Carbonic Anhydrase 9 (CA9) positive viable tumour cells which filled the vessel lumen." (PMID 40295487, 2025). "We compared the immunohistochemical expression of CD34, VASH1, and carbonic anhydrase 9 (CA9) between patients who achieved tumor clearance at operation (ypT0) and those with residual disease after cystectomy." (PMID 38376711, 2024). "The accumulation of pimonidazole was modest in well-perfused area within tumor, and high in poor-perfused area; as the accumulation of CA9." (PMID 38947402, 2024). "Owing to its limited expression in normal cells as well as responsiveness in hypoxic tumor microenvironment, CA9 was proposed to be more druggable candidate as compared to CA12." (PMID 38530845, 2024). "Adjacent dysplastic tissue of HNSCC has shown an overexpression of hypoxia marker carbonic anhydrase 9 (CA IX), indicating high OC and insufficient O2 replenishment not only in the tumor tissue itself, but also in dysplastically altered surrounding tissue." (PMID 38390268, 2024). "Sildenafil-treated mock HCT116 tumours (B) had higher levels of CA9 protein and pimonidazole stain which are markers for chronic and short-term hypoxia, respectively." (PMID 38350962, 2024). "Together, these results expand our understanding of the cancer-associated function of lncRNAs, highlighting the ZNF674-AS1/IGF2BP3/CA9 axis as a constituting regulatory mode in NB tumor growth and cisplatin resistance." (PMID 38177154, 2024). "It has been reported that the expression of CA9 in tumor cells indicates the presence of a hypoxic tumor environment." (PMID 39471162, 2024). "Another recent study found that HIF-1α prevents tumor cells from being subjected to immune surveillance with enhanced levels of carbonic anhydrase IX (CA9) expression." (PMID 37588219, 2024). "Carbonic anhydrase 9 (CA9) is considered a marker of hypoxia and it has reported that CA9 is associated with tumor invasion and metastasis." (PMID 39471162, 2024). "IHC indicates the tumor cells were nuclear positive for CA9, CD10, vimentin, and EMA, which suggest the pathological diagnosis of ccRCC." (PMID 39080639, 2024). "The combined Ref-1 and CA9 inhibition produced enhanced tumor cell killing even in the protective environment of the tumor stroma." (PMID 39635662, 2024). "Studies demonstrated that a cooperative function between cytosolic CA isoforms (CA1 and CA2) and membrane-associated CAs (CA9, CA12 and possibly CA14) is important for pH regulation between the extracellular and intracellular tumor environment." (PMID 38530845, 2024). "Specifically, carbonic anhydrase 9 (hCAIX) and carbonic anhydrase 2 (hCAXII) are crucial in acidifying the tumor environment and promoting tumor cell invasion and metastasis." (PMID 39104400, 2024). "Given the elevated expressions in different cancer types, CA9 and CA12 are considered as tumor-associated CAs, and thus are most studied CA isoforms in respect to tumor settings." (PMID 38530845, 2024).
tumor (continued). "In the ypT0 cohort, high MVD, high VASH1 density, and strong CA9 staining were observed more frequently in patients who achieved tumor clearance at the time of the operation." (PMID 38376711, 2024). "A recently developed biophysical model suggests a role for carbonic anhydrase 9 (CA9) as a marker of tumor aggressiveness." (PMID 37568758, 2023). "Taken together, these results confirm that IGFL2‐AS1 can maintain CRC tumor growth through the HIF‐1α/CA9 pathway in vivo." (PMID 36537608, 2023). "Pixel intensity–based colocalization analysis across each of these tumor sections found that anti-GFP stain fluorescence intensity had the strongest correlation with anti-CA9 stain fluorescence intensity, with a mean Pearson r ̄ of 0.84 (SD = 0.09)." (PMID 37285434, 2023). "Co-localization of CP and CA9 proteins using IF staining validated tumor cell-specific CP expression." (PMID 36973268, 2023). "Specifically, epithelial cells dominated all major cell compartments, with tumor epithelial cells expressing the canonical markers of CA9 coming exclusively from tumor tissues and normal epithelial cells having multiple origins." (PMID 37153569, 2023). "CA9 catalyzes the reversible hydration of carbon dioxide to bicarbonate, allowing tumor cells to maintain a neutral pH level inside the cell, while acidifying the extracellular microenvironment." (PMID 37443682, 2023). "A recent study showed that the upregulation of CA9 significantly inhibits tumor cell ferroptosis under hypoxia." (PMID 36760347, 2023). "ccRCC tissues from patient nephrectomy specimens were dispersed into single-cell suspensions and analyzed for HHLA2 expression after CA9 positive selection for tumor cell purification." (PMID 37891555, 2023). "CA9 is abundantly expressed in many cancer types where it maintains the normal pH level in tumor cells in the hypoxic environment." (PMID 36768453, 2023). "The study results showed that the reduction in expression levels of all four investigated genes, CA9, NDUFA4L2, EGLN3, and BHLHE41, is associated with tumor metastasis." (PMID 37443682, 2023). "In hypoxic environments, RCC tumor cells secrete EVS containing/expressing Carbonic Anhydrase 9 (CA9)." (PMID 37834162, 2023). "The five remaining articles focused on the Epstein–Barr virus (EBV), proliferating cell nuclear antigen (PCNA), carbonic anhydrase 9 (CAIX), tumor–stroma ratio, or tumor-infiltrating lymphocytes." (PMID 37894447, 2023). "It is well established that hypoxic conditions in tumor cells induce CA9 expression through the HIF transcription factor, which binds to the HRE site in the CA9 promoter." (PMID 37285434, 2023). "In contrast to other ALCLs, a hypoxia gene signature with higher CA9 expression by the tumor cells has been observed in BIA-ALCL." (PMID 37555981, 2023). "Some researchers associate decreased CA9 expression in patients with poor prognosis with the activation of AKT and mTOR pathways, which makes further tumor growth less dependent on hypoxia and shifts it to an alternative pathway." (PMID 37443682, 2023). "CA9, which has a catalytic domain facing outside the cell membrane, is an enzyme that plays a central role in tumor pH regulation, and it catalyzes the balance between H+, CO2, and HCO3− inside and outside the cell." (PMID 36537608, 2023). "The transmembrane protein CA9 has a similar property as heat shock proteins (HSPs) in cytoskeletal networks of tumor cells by regulating cytosolic filaments." (PMID 36760347, 2023). "Even though the expression of HIF1α and CA9 was the same in these two groups, tumor tissues derived from mice injected with HepG2 cells overexpressing CFHR3 had lower PCNA expression levels." (PMID 35549979, 2022). "Carbonic anhydrase IX (CA9) is a cell-surface glycoprotein in the tumor, expression of which is induced by hypoxia and has been shown to be involved in cancer progression." (PMID 35664073, 2022).
tumor (continued). "We performed binding assays to test the dual specificity of the purified DATEs for CD3 on T cells and CA9 on patient-derived tumor cells." (PMID 35874663, 2022). "Our FACS analysis showed increase in CA9 positive cells–marker of ccRCC–with samples from higher tumour grade, confirming presence of ccRCC cells." (PMID 35102500, 2022). "Our data demonstrates long term efficacy of the DATE in tumors with CA9 expressed homogeneously throughout the tumor at a high level, yet short term efficacy in models where the proportion of CA9 positivity is lower." (PMID 35874663, 2022). "Another interesting finding was the significant association of the overexpression of three hypoxia and acidity-related markers, namely, HIF1α, HIF2α, and CA9, with an immunologically cold tumor microenvironment." (PMID 35735451, 2022). "So, we stained healthy pancreas and KPC tumor tissues with carbonic anhydrase 9 (CA9), indicative of hypoxia." (PMID 35626052, 2022). "The expression of CA9 was predominantly found in perinecrotic tumor cells, but the positive expression of HIF-1α, nestin, and FOXM1 was widely distributed." (PMID 35785200, 2022). "Then we performed IHC detection of CA9, where multivariate analysis is significant, and confirmed that it was highly expressed in tumor tissues." (PMID 34878732, 2022). "In particular, carbonic anhydrase 9 (CA9), as a cellular biomarker and pH regulator of hypoxia, is overexpressed in cells in the abnormal vasculature and tumor microenvironment." (PMID 36516252, 2022). "The indirect stabilization of HIF-1α by lactate also contributes to activation of the carbonic anhydrase 9 (CA9) gene, encoding the transmembrane protein of the family of carbonic anhydrases (CAIX), which maintains a constant acidic pH in the tumor tissue." (PMID 35205136, 2022). "The presence of OPN in CA IX positive tissues is in line with investigations of tumor tissues which showed a positive correlation between CA9 and SPP1 mRNA expression in different types of cancer." (PMID 35055064, 2022). "Tumor cells were identified within clusters that specifically expressed CA9 and harbored extensive copy-number variations (CNVs) across their genomes, as inferred from scRNA-seq data." (PMID 36423636, 2022). "To target CA9 expressing tumor cells, we exploited the cell surface localization and generated DATEs." (PMID 35874663, 2022). "To evaluate the effect of the CA9 DATE on tumor growth in vivo we evaluated the RCC243 model where CA9 expression is highly, homogeneously expressed throughout the tumor." (PMID 35874663, 2022). "Treatment with 32-134D also inhibited hypoxia-induced expression of SLC2A1, LDHA, ENTPD1, and CA9 mRNA, which play roles in both tumor metabolism and immune evasion (P < 0.05)." (PMID 35499076, 2022). "DRS measurements were correlated to end-point immunohistochemistry (IHC) markers of hypoxia (carbonic anhydrase-9) and microvasculature (CD31), along with tumor-associated macrophage recruitment (CD68) and M2 tumor-associated macrophage recruitment (CD163)." (PMID 35461243, 2022). "In contrast, Ca9-22 tumor masses treated with 50 μM resveratrol showed markedly reduced expression of SREBP1 and E-FABP mRNAs, whereas p62 mRNA was expressed only slightly." (PMID 36500345, 2022). "Together, our results confirmed antigen specificity and high affinity binding of CA9 DATEs to the tumor cells and T cells." (PMID 35874663, 2022). "Converging observations have indicated that CA9 is functionally involved in diverse hallmarks of cancer, such as promotion of primary tumor growth and metastatic dissemination." (PMID 35812185, 2022). "The fact that this strategy requires both the target antigen to be expressed (CA9) and the T cells to be in the same location likely adds safety to the approach and potentially mitigates the concerns about on-target-off-tumor toxicity." (PMID 35874663, 2022).
tumor (continued). "Among the 15 isoforms known in humans, 2 cell-surface CA isoforms, namely, CA9 (or CA IX, almost exclusively associated with tumors) and CA12 (or CA XII, upregulated in some tumor types), are involved in tumorigenesis." (PMID 35362480, 2022). "Knockdown of MT1X in the setting of hypoxia reduces the accumulation of HIF-1α, EPO, VEGF, and CA9, which are important factors that regulate tumor cell adaptation to hypoxia (P<0.05)." (PMID 36149322, 2022). "CA9 is commonly related to tumour radio and chemoresistance due to its role in maintaining cellular homeostasis in hypoxic conditions, allowing tumour cell detection and, as a result, aggressive tumour phenotypic traits." (PMID 36415514, 2022). "It targeted ALDO, LDHA, ENO1, PGK1, CA9, and other genes in the invasive tumor and the hypoxic tumor." (PMID 36685583, 2022). "In the present study, “pseudo-papillary” structures containing nestin+/FOXM1+ cells in the perivascular niche and CA9/HIF-1α positivity in the area surrounding stem cell accumulation resembled co-opted tumor vessels and were observed in refractory-Bev." (PMID 35785200, 2022). "Carbonic anhydrase 9 (CA9) is a transcription factor that responds to a reduction in the oxygen supply in the tumour microenvironment." (PMID 36415514, 2022). "In the current study, we observed a correlation between high levels of inflammatory markers (NLR and CRP) and tumor expression of CA9 and SLC2A1, which further supports the interplay between hypoxia and inflammation in MPNST." (PMID 33810575, 2021). "CA9 can be targeted in order to turn an abnormal (immature) tumor vasculature into normal (mature) vessels." (PMID 35145911, 2021). "Among all the candidates, we focus on DNMT1 because a DNA methylation-involved regulation on CA9 has been recently suggested in a subset of tumor cells." (PMID 34493285, 2021). "The GLUT1, MCT4, and CA9 are markers of metabolic adaptation to hypoxia and acidosis contributing to tumor aggressiveness, recurrence, and the poor prognosis of patients." (PMID 35008313, 2021). "As the tumor develops, its size also increases, which can lead to difficulty in removing H+, the formation of which is catalyzed by CA9 from the tumor space and the tumor microenvironment where it accumulates." (PMID 34046336, 2021). "We found that knockdown of CA9 resulted in a remarkable decrease of tumor cell progression in TSCC15 cells." (PMID 34493285, 2021). "CA9 has been identified as a hypoxia-dependent gene that is particularly relevant for the stem cell niche, in which GSCs can survive tumor-targeted therapies." (PMID 35008590, 2021). "Recent in vivo studies showed that the use of MCM2/CA9 inhibitors, such as ciprofloxacin and acetazolamide, respectively, in combination with cisplatin, improve mice overall survival and reduce tumor nodule growth." (PMID 33921816, 2021). "Among the genes associated with the malignant stage, minichromosome maintenance complex 2 (MCM2) and carbonic anhydrase 9 (CA9) show a positive correlation with tumor growth, and these genes are potential targets for therapeutic strategy." (PMID 33921816, 2021). "Genes whose upregulation is associated with some cancers (TMEM140, ANXA10, ZNF69, CA9, LOXL2, PAGE3, ELFN1) were also on this list, as was a putative tumor suppressor (DEC1)." (PMID 33601339, 2021). "In the early stages of tumor development, increased expression of CA9 is required as an adaptation factor for hypoxia." (PMID 34046336, 2021). "Some tumor biomarkers varied as the cell cycle progressed, such as CA9, TK1 and EGFR, which were more abundantly expressed at early S stage." (PMID 34691667, 2021). "HIF-1α binds to hypoxia response elements and regulates changes in the expression of different factors, such as VEGF, plasminogen activator inhibitor-1 (PAI-1) and carbonic anhydrase 9 (CAIX), promoting neovascularization and favoring tumor spread." (PMID 33445558, 2021).
tumor (continued). "The results obtained using a HypoxiSenseTM-680 fluorescent imaging agent that detects carbonic anhydrase 9 (CA IX) tumor cell surface expression revealed a rise of hypoxia in shLRP-1 tumors compared to shCtrl (0.079 ± 0.020 vs. 0.010 ± 0.04 pmol/mm3)." (PMID 34680548, 2021). "We targeted carbonic anhydrase 9 (CA9), an enzyme associated with remodeling the tumor pH environment, and integrin-α11β1, a heterodimeric receptor involved in cancer-associated fibroblast biology." (PMID 33980972, 2021). "CA9, a well-known hypoxia-induced gene, plays critical roles in promoting tumor progression and hypoxia adaptation." (PMID 34493285, 2021). "RNA-sequencing in 887S or 887L loss-of-function cells identified their common downstream target as Carbonic Anhydrase IX (CA9), a gene known to be upregulated by hypoxia during tumor progression." (PMID 34493285, 2021). "We then evaluated the correlation between tumor size and the most differentially expressed hypoxic marker, CA9." (PMID 33806378, 2021). "Although CA9 expression is reduced as the tumor progresses through the stages of ccRCC, even at stage IV its levels of expression never fall below those observed in normal tissues." (PMID 34046336, 2021). "Previous work has reported that CA9 is transcriptionally activated by HIF1α in a broad spectrum of tumor cells." (PMID 34493285, 2021). "The transmembrane protein CA9 responded to hypoxia that regulates intracellular pH by acidifying tumor microenvironment that endorses tumor growth, survival, and invasiveness." (PMID 33990544, 2021). "Further, it was observed that Tan IIA markedly reduced the protein expression of CA-9 in the tumor parenchyma, implying that the hypoxia microenvironment was ameliorated with the achievement of vascular normalization." (PMID 34804370, 2021). "Next, we compared the mRNA levels of SPINK1 with those of one of the most representative intrinsic hypoxia markers, CA9, in 36 subcutaneous HeLa tumor xenografts by qPCR." (PMID 34747365, 2021). "CA9 is a zinc metalloenzyme that facilitates tumor acidification through hydration of carbon dioxide." (PMID 34493285, 2021). "To study if this overcoming of immune evasion by inhibition of IL6 signaling is due to decreased lactate efflux by tumor cells, we inhibited lactate efflux by inhibiting CA9." (PMID 33177492, 2020). "Our in silico analysis of 179 PDAC samples and 171 normal pancreas samples derived from the cancer genome atlas (TCGA) and GTEx datasets showed upregulation of all analyzed genes as well as CA9 in tumor samples compared to healthy tissues." (PMID 32707920, 2020). "CA9 is expressed at low level only in few normal tissues, whereas it is over-expressed in several solid tumors in which, as a consequence of tumor hypoxic environment, converts CO2 to HCO3− and H+." (PMID 33153038, 2020). "Although hypoxia increased the recruitment of BRD4 to CA9 and VEGF-A in tumor cells, the down-regulated CA9 and VEGF-A in tumor cells treated with JQ1 indicated that JQ1 affected the hypoxia response in which BRD4 participated." (PMID 33109235, 2020). "In tumor tissues, we found an increased expression of CA9, CD70, and CD147 were increased in cell lysates and EV fractions compared to normal tissues." (PMID 33276608, 2020). "CA9 displays alterations in tumor metabolism and acid/base regulation, therefore enhancing tumor growth and metastasis." (PMID 33276608, 2020). "Univariate and multivariate Cox regression analyses indicated that CA9 expression correlates with tumour grade." (PMID 32299152, 2020). "We then used Kaplan Meier survival analysis of patients’ RFS and found that PD-L1 co-expression with NFKB2 (p < 0.001) and also with CA9 expression; a hypoxic biomarker significantly predicted tumor progression in our cohort (p = 0.001)." (PMID 32839486, 2020). "Immunoreaction for CA9 resulted in diffuse staining in 17 tumor samples, and focal staining in 4 tumor samples." (PMID 31656019, 2020).